REN (renin)
Diseases named in the same sentence as REN in open-access papers (continued):
Sharing a sentence is not in itself a finding about the gene and the disease.
Hypertension (continued). "Pathophysiology of hypertension in SHR is due to overall changes in RAS components, such as renin activity, ACE activity, angiotensin II content, AT1 receptor expression, and NADPH oxidase activity." (PMID 32325920, 2020). "The interplay between AHR, nitric oxide (NO), the renin–angiotensin system (RAS), and gut microbiota is involved in the development of hypertension." (PMID 32604820, 2020). "The renin–angiotensin–aldosterone system (RAAS) has a broad impact on blood pressure regulation and hypertension in the pediatric population." (PMID 32640705, 2020). "Activation of the renin-angiotensin-aldosterone system (RAAS) and chronic immune activation contribute to the development of MetS and hypertension in PWH." (PMID 32880756, 2020). "In conclusion, possible mechanisms of hypertension resistant to ACEi/ARB observed in certain cancer patients include overexpression of Angiotensin II receptor 1, low renin state or RAAS suppression." (PMID 32864163, 2020). "The increase of Angiontesin-II (Ang-II), one of the key peptides of the renin-angiotensin system (RAS), and its binding to the Ang-II type 1 receptor (AT1R) during hypertension is a crucial mechanism leading to AD\AM17 activation." (PMID 32848763, 2020). "For example, the lack of CEACAM-1, a key protein enrolled in hepatic insulin clearance driving hyperinsulinemia, in the kidney leads to increased renin levels contributing to a potentiation of the RAS system and hypertension." (PMID 32850773, 2020). "Feeding a high phosphate diet was shown to increase renin expression via PTH in healthy rats, which in turn stimulated AngII, and thereby induced hypertension." (PMID 31698866, 2019). "Activation of the renin-angiotensin system (RAS) leads to fibrosis in various organs through its direct effect and the resultant hypertension, and activation of the immune system." (PMID 32039229, 2019). "State-of-the-art clinical management of arterial hypertension includes, pharmacological targeting of the RAAS with ACE-inhibitors, AT1R blockers, direct renin inhibitors, and aldosterone antagonists." (PMID 31052201, 2019). "DOCA-salt rat is characterized by low renin-AngII levels, and BBB permeability is sustained in the early stage (at least 3 weeks after DOCA-salt administration) of hypertension in DOCA-salt rat." (PMID 30971251, 2019). "Interestingly, some recent reports have described that a more profound and global GRK2 knockdown may be detrimental due to enhanced renin- and AT1R-mediated reactive oxygen species (ROS) production that can cause renal damage and the development of hypertension with age." (PMID 30837878, 2019). "Furthermore, vitamin D’s protective effect against atherosclerosis and hypertension was explained by its ability to decrease the proliferation of vascular smooth muscle, decrease calcium influx into endothelial cells, decrease vascular resistance, and regulate the renin–angiotensin system." (PMID 31635396, 2019). "Renin in turn transforms angiotensinogen into angiotensin I, which is then converted into angiotensin II by ACE, resulting in hypertension." (PMID 31379972, 2019). "Treatment intensification to achieve control of hypertension by means of agents such as ACE inhibitors and spironolactone that act via the renin–angiotensin system is clearly warranted both to preserve renal function and reduce protein loss." (PMID 31461449, 2019). "The pharmacological class of direct renin inhibitors (DRI), which are used predominantly to treat hypertension, work through high-efficiency binding to active renin." (PMID 31261774, 2019). "Low calcium levels are also concomitant with an increased release of renin from the kidneys, influencing maternal circulating renin-angiotensin-aldosterone systems (RAAS) leading to hypertension through vasoconstriction and fluid/sodium retention." (PMID 30609706, 2019).
Hypertension (continued). "Hypertension in patients with PRES is usually secondary to treatment (steroids, cyclosporin), low serum magnesium levels or renin-angiotesin-aldosteron system response to tumour-compressing renal vasculature." (PMID 29198072, 2018). "Inhibitors against renin (aliskiren) and angiotensin (losartan), components of renin–angiotensin–aldosterone system (RAAS), both significantly suppressed cold-induced hypertension and plasma aldosterone levels increased due to cold exposure in mice." (PMID 29560109, 2018). "The activation of the renin-angiotensin system (RAS) is a crucial factor in the development and progression of organ damage in hypertension, diabetes and CDK." (PMID 29941815, 2018). "Therefore, renin inhibitors may be good candidates for prenatal GC exposure related hypertension." (PMID 29540174, 2018). "Moreover, since heart remodeling is associated with the activation of angiotensin II or aldosterone, we investigated whether the potential effects of ivabradine in L-NAME-hypertension are related to its interference with the renin-angiotensin-aldosterone system (RAAS)." (PMID 30282928, 2018). "Thus, identifying the contribution of intravascular volume and serum renin in maintaining BP levels could help tailor more effective hypertension treatment, whether by acting on the control of intravascular volume or sodium balance, or by acting on the effects of the RAAS on the kidney." (PMID 29433578, 2018). "Renin–angiotensin–aldosterone system (RAAS) plays important roles in regulating renal hemodynamics and functions, as well as in the pathophysiology of hypertension and renal disease." (PMID 29600408, 2018). "Thus, identifying the contribution of blood volume and serum renin in maintaining BP levels could help tailor more effective hypertension treatment, whether by acting on the control of blood volume, the sodium balance, or by acting on the effects of the RAAS on the kidney." (PMID 29433578, 2018). "Cross talks between the renin-angiotensin system (RAS), sympathetic nervous system, and vascular homeostasis are tightly coordinated in hypertension." (PMID 30510587, 2018). "Pharmacological inhibitors targeting the RAS cascade, in particular renin inhibitors, ACE inhibitors and angiotensin receptor antagonists, have proved to be highly effective for the treatment of hypertension." (PMID 30518571, 2018). "AGT and ACE are part of Renin-Angiotensin System pathway (KEGG, map04614), involved in BP homeostasis, fluid-electrolyte balance, and essential hypertension." (PMID 29912962, 2018). "Pruijm studied the role renin-angiotensin system (RAS) in renal oxygenation in early stage type 2 diabetic patients with evidence of nephropathy (albuminuria and/or hypertension)." (PMID 28701959, 2017). "ENPEP is involved in the catabolic pathway of the Renin-angiotensin System (RAS) forming angiotensin III, which participates in blood pressure regulation and blood vessel formation, and may contribute to risk of atrial fibrillation, angiogenesis, hypertension and tumorigenesis." (PMID 29900035, 2017). "Our results, furthermore, suggest that the development of volume loading hypertension may be aggravated in the black population through excessive alcohol consumption as indicated by the association of percentage change in renin with GGT levels, although not a focus of this article." (PMID 28446166, 2017). "This is thought to be due to the fact that, prior to menopause, oestrogens in females are capable of modulating the renin-angiotensin-aldosterone system (RAAS) in a manner that reduces the development and/or progression of hypertension." (PMID 29099025, 2017). "The previous studies suggest that activation of renin-angiotensin system (RAS), reduction of endothelial nitric oxide levels and endothelial dysfunction are potential mechanisms of hypertension in human and animal models of HN." (PMID 29340054, 2017).
Hypertension (continued). "The renin-angiotensin system (RAS) plays an important role in primary and secondaryforms of hypertension." (PMID 28678925, 2017). "The inhibition of the renin, ACE-I, and DPP-IV enzymes has therefore become a key therapeutic target for the treatment of hypertension and diabetes." (PMID 29207547, 2017). "Exercise training reduces renin-angiotensin system (RAS) activation, decreases plasma and tissue oxidative stress and inflammation in hypertension." (PMID 29232407, 2017). "Renin and ACE activity are used as biomarkers for disease states such as hypertension, diabetes, heart failure and renal diseases." (PMID 28423630, 2017). "Renin and ACE are the two pivotal enzymes that regulate the renin-angiotensin system (RAS), which plays a crucial role in the pathogenesis of hypertension." (PMID 29151830, 2017). "The pathophysiology of hypertension in OSA is complex and is dependent on various factors such as sympathetic tone, peripheral vasoconstriction, increased renin-angiotensin-aldosterone activity, and altered baroreceptor reflexes." (PMID 29147581, 2017). "Renin catalyzes the initial rate-limiting step within the RAAS, and is therefore an important target for the treatment of high blood pressure." (PMID 28445408, 2017). "All patients had hypertension and were taking antihypertensive medication, with renin-angiotensin system (RAS) inhibitors including ARBs, ACE inhibitors, and direct renin inhibitors being the most common, followed by calcium channel blockers." (PMID 26839894, 2016). "On the other hand, because renin gene transcription is strictly regulated to maintain blood pressure homeostasis, it is quite intriguing that THM exhibits severe hypertension." (PMID 27861631, 2016). "However, whether CD renin is involved in Ang-II independent hypertension is currently unknown." (PMID 27467376, 2016). "High levels of mouse-transgene-derived inactive renin, and low levels of active renin, were produced in the adrenal gland, indicating that tissue RAAS is responsible for hypertension in this model." (PMID 27935823, 2016). "Given the importance of the renin-angiotensin-aldosterone system (RAAS) in human DN, several researchers have employed transgenic rodents in which the RAAS is overactivated to induce hypertension and accelerated DN." (PMID 26814757, 2016). "Thus, the renin gene transcription is regulated by the WT-1 (−KTS) protein and this could explain the findings in patients with WT-1 mutations that occur with increased plasma renin and hypertension." (PMID 27009470, 2016). "Consequently, CD renin might also be up regulated in L-NAME hypertension." (PMID 27467376, 2016). "The enzyme renin plays a key role in the RAAS cascade and an important role in the development of hypertension and progression of renal disease in ADPKD." (PMID 26753721, 2016). "Expression of either REN or KLKB1 was regulated in cell line and rodent models of hypertension in response to oxidative stress, interleukin or arterial blood pressure changes." (PMID 26969407, 2016). "Several biological mechanisms, such as activation of renin-angiotensin system (RAS) and sympathetic nervous system, are involved in the development of obesity-related hypertension." (PMID 27558088, 2016). "Thus, we hypothesize that the improvement of insulin resistance, sympathetic nerve and renin-angiotensin system overactivity along with vascular remodeling and function could alleviate high blood pressure and alleviate cardiovascular complications in diet-induced MS rats." (PMID 27121076, 2016). "This review emphasizes the detrimental effects that a renin-angiotensin-aldosterone system (RAAS) imbalance has on health considerations above and beyond high blood pressure, such as fibrotic end-organ damage." (PMID 27347925, 2016).
Hypertension (continued). "In the present study, we show that long-term treatment of SHR with PEA alleviates hypertension, by improving EDHF-mediated vasodilation, through the modulation of EET hydrolisis and renin-angiotensin system in the vasculature." (PMID 25951330, 2015). "Here, we investigated the effect of H2S on plasma renin activity and BP in rat models of STZ induced DN hypertension." (PMID 26221579, 2015). "We for the first time demonstrate the renin regulatory function of PRR in vivo and in vitro and report PRO20 as a novel therapeutic agent for hypertension and chronic kidney disease." (PMID 26554902, 2015). "Taken together with the renin profiling and detailed physiological phenotyping, the PATHWAY 2 study will be recruiting the most precisely defined resistant-hypertension population to date." (PMID 26253568, 2015). "Angiotensin (Ang) II is the major bioactive peptide of the renin–angiotensin system (RAS); it contributes to the pathogenesis of hypertension by inducing vascular contraction and adverse remodeling, thus elevated peripheral resistance." (PMID 26011449, 2015). "The median renin in PATHWAY-2, 34 mU/L, is roughly three times higher than that in the PATHWAY-1 study, of 600 patients with untreated hypertension (unpublished)." (PMID 26414968, 2015). "Hypertension may also be mediated through increased vascular and sympathetic tone created by reduced bioavailability of nitric oxide (NO) because of oxidative stress, and increased expression of angiotensinogen by adipose tissue leading to an activation of the renin-angiotensin system." (PMID 25774201, 2015). "The activation of the renin-angiotensin-aldosterone system (RAAS), such as aniotensin II (Ang II) or aldosterone (Aldo), plays an important role in the pathogenesis of hypertension and chronic kidney damage via the production of inflammation." (PMID 26556241, 2015). "Therefore, additional long-term experiments may be able to reduce arterial blood pressure accompanied by improvement in vascular function, but hypertension cause, such as the renin-angiotensin system disorders, has not been removed." (PMID 26693246, 2015). "Clinical consequences of this renin-angiotensin-aldosterone system (RAAS) activation are peripheral vasoconstriction and salt retention leading to systemic hypertension." (PMID 25177679, 2014). "Several studies in vitro and in vivo studies suggest the existence of cross-talk between TNFα and the renin-angiotensin system (RAS), which is an important part of the pathogenesis of hypertension." (PMID 24665369, 2014). "MDK levels are increased in systemic hypertension and MDK interacts with ACE in the renin-angiotensin system." (PMID 25329529, 2014). "In the kidneys of both humans and experimental models, developmental programming reduces nephron numbers, alters the renin-angiotensin system (RAS), and impairs natriuresis, leading to adult kidney disease and hypertension." (PMID 24864188, 2014). "In this way, MS-based proteomics is a robust tool in the research of the complex protease network such as the renin-angiotensin system (RAS), a widely investigated proteolytic network with a central role in hypertension development." (PMID 24877123, 2014). "There is a close relationship between the Renin-Angiotensin-Aldosterone (RAS) system and hypertension." (PMID 24465407, 2014). "The clipping of an artery supplying one of the two kidneys (2K1C) activates the renin-angiotensin (Ang) system (RAS), resulting in hypertension and endothelial dysfunction." (PMID 25223948, 2014). "Considering the close mechanistic relationship between apelin/AGTRL1 system and the renin-angiotensin system, it is logical to make AGTRL1 gene as a candidate gene for hypertension." (PMID 24465893, 2014). "Moreover, low-renin hypertension and PA may also share elevated ARR." (PMID 24235884, 2013). "To provoke hypertension, we challenged NO-GC1 KO mice with the 2K1C operation, which activates the renin-angiotensin-aldosterone system (RAAS)." (PMID 24260450, 2013).
Hypertension (continued). "Renin expression is highly elevated in VDR null mice, which leads to systemic hypertension, cardiac hypertrophy and heart failure." (PMID 23889806, 2013). "Renin-angiotensin system (RAS) plays a pivotal role in blood pressure regulation, salt and water balance, and in the pathophysiology of renal failure and hypertension." (PMID 23847460, 2013). "Plasma aldosterone concentration (PAC) and renin activity levels (PRA) should be obtained and a PAC/PRA ratio calculated in patients with hypertension to screen for primary hyperaldosteronism." (PMID 23401807, 2013). "Plasma renin activity (PRA) is an essential analytical tool for screening and diagnosis of secondary forms of hypertension." (PMID 24359218, 2013). "In addition, enhanced salt sensitivity, activated renin-angiotensin-aldosterone system, potentiated procoagulatory activity, and induced endothelial dysfunction among obese individuals may be also responsible for the development of hypertension." (PMID 23109900, 2012). "From these publications, we believe that MDM2 and IGN1 should be part of the apoptosis list, as well as REN and ADIPOQ should be part of the hypertension list." (PMID 23282288, 2012). "An important hypothesis in the pathogenesis of essential hypertension involves an interaction between high dietary sodium intake and defects in renal sodium excretion, which can be influenced by sympathetic neural activity and the renin-angiotensin-aldosterone system." (PMID 22216059, 2012). "In the transgenic mRen-2 rat model, levels of plasma and tissue renin and other RAS components are altered, leading to hypertension." (PMID 20441574, 2010). "The renin-angiotensin system (RAS) plays a pivotal role in the progression of renal disease, as well as in hypertension and target-organ damage." (PMID 20920303, 2010). "Signals that promote renin synthesis and secretion can lead to RAAS-dependent hypertension in humans." (PMID 20613959, 2010). "Numerous studies have reported that chymase, acting as an important component of the local renin-angiotensin system (RAS), is activated in vascular disease conditions, such as hypertension and atherosclerosis." (PMID 20356378, 2010). "Aliskiren has the potential to become the first orally active renin inhibitor that provides a true alternative to ACE-inhibitors and Ang II receptor antagonists in therapy for hypertension and other cardiovascular and renal diseases." (PMID 27713228, 2009). "Unlike hypertension studies linking TyG to kidney disease, our MR demonstrates that renal signals are secondary to systemic inflammation/renin-angiotensin-aldosterone system (RAAS) activation." (PMID 41056021, 2026). "It was shown that the renin–angiotensin–aldosterone and sympathoadrenal systems do not play a primary role in the development of hypertension in this animal model." (PMID 40722594, 2025). "Conversely, hypertension pathogenesis is largely driven by separate mechanisms, such as renal sodium handling, vascular resistance, and the renin-angiotensin system, in which FTO does not play a well-established central role." (PMID 41340966, 2025). "Affected 46,XY individuals with isolated 17,20-lyase deficiency exhibit low sex hormone secretion and atypical genitalia, normal glucocorticoid and mineralocorticoid secretion, and absence of low-renin hypertension." (PMID 40313596, 2025). "Additionally, HRP significantly decreased AT1R protein expression and increased the expression of MASR and ACE2, reversing the renin-induced activation of RAS in HepG2 cells, which is closely related to the improvement of hypertension." (PMID 40650317, 2025). "In other conditions such as renal pseudohypoaldosteronism type 1 the ARR can be high with very high aldosterone concentrations, but renin concentrations are not suppressed, and the patients do not have hypertension." (PMID 40309437, 2025).